EGFR (epidermal growth factor receptor)
Diseases named in the same sentence as EGFR in open-access papers (continued):
Sharing a sentence is not in itself a finding about the gene and the disease.
lung cancer (continued). "The discovery of specific SIRT regulation and EGFR-TKI treatment would help elucidate the roles of sirtuins in lung cancer development." (PMID 31956359, 2020). "Subsequent work showed that EGFR TKI activation of Notch 3 in EGFR-mutant lung cancer cells is accompanied by stabilisation and activation of β-catenin." (PMID 32575680, 2020). "The present systematic review confirms the existence of some “good” quality evidence to support the role of peculiar salivary biomarkers for diagnosis of systemic diseases (e.g. lung cancer and EGFR)." (PMID 32040469, 2020). "In recent years, the treatment of non‐small cell lung cancer (NSCLC), especially with EGFR inhibitors, has made rapid progress, and the median progression‐free survival (PFS) of patients with EGFR gene‐sensitive mutations has been significantly prolonged." (PMID 32776462, 2020). "In conclusion, HB-EGF played an important role in As-T cells, and activated EGFR and downstream signal pathways in lung cancer." (PMID 32695675, 2020). "The EGFR mutations can be readily detected in BW-derived EVs, which demonstrates their clinical potential as a liquid-biopsy sample that may aid precise management, including assessment of the treatment response and drug resistance in patients with lung cancer." (PMID 33007940, 2020). "We and others have previously reported that NF-κB was activated in EGFR-mutant lung cancer with acquired resistance to EGFR TKIs." (PMID 33014814, 2020). "In comparison to normal lung tissue and para-cancerous tissue, lung cancer cells show significantly higher EGFR expression." (PMID 33247670, 2020). "Taken together, our data demonstrate metformin as a potential candidate for combination therapy for EGFR-mutant lung cancer." (PMID 33014814, 2020). "We also show that mitochondrial cholesterol levels are upregulated in lung cancer cells exposed to EGFR TKIs." (PMID 32123859, 2020). "Now that EGFR-TKI therapy dramatically improved the prognosis for EGFR mutated NSCLC, the detection of such mutations is a critical step when managing lung cancer patients." (PMID 32028905, 2020). "EGFR is one of the most prevalent genetic alterations among lung cancer patients, even though other genetic aberrations also exist." (PMID 32850378, 2020). "When combined with EGFR TKIs gefitinib or osimertinib, metformin had synergistic effects on the proliferation of lung cancer cells." (PMID 33014814, 2020). "The majority of lung cancer cases are classified as NSCLC, which is often associated with mutations in the driving gene EGFR." (PMID 32854390, 2020). "Here, using a barcoding approach applied to large cell populations, the authors explore evolutionary steering in lung cancer cells treated with EGFR inhibitors." (PMID 32317663, 2020). "For instance, in lung cancer, miR-646 suppresses cell proliferation and metastasis by negatively regulating the EGFR/Akt pathway; in colorectal cancer, miR-646 represses NOB1 to inhibit cancer progression." (PMID 32669977, 2020). "In lung cancer, EGFR has become a crucial therapeutic target for patients with non-small-cell lung cancer." (PMID 32685551, 2020). "We hope our study provides further molecular rationale and preclinical data to support combination of metformin with EGFR TKIs to treat lung cancer." (PMID 33014814, 2020). "Even after therapy failure, lung cancer patients were shown to respond to EGFR (Epidermal Growth Factor Receptor) treatment following a short period of drug holiday." (PMID 32365663, 2020). "The subsequent discovery of somatic alterations in the tyrosine kinase domain of the EGFR gene provided an explanation as to why only a fraction of lung cancer patients had excellent response to EGFR TKIs." (PMID 32292420, 2020). "Taken together, these results demonstrated that EGFR-TKIs inhibited lung cancer progression and metastasis by suppressing lymphangiogenesis in vitro and in vivo." (PMID 31892990, 2020).
lung cancer (continued). "For example, treatment of EGFR mutant lung cancer cells with EGFR-targeted inhibitors resulted in inflammation mediated by cytokines, chemokines, type 1 IFN as well as recruitment of innate immune cells." (PMID 33213500, 2020). "Lung carcinomas are highly proliferative and resistance acquisition after EGFR TKI-based therapy is a major problem." (PMID 32438613, 2020). "Several observations suggest that high glycolytic metabolism favors resistance to EGFR inhibitors in lung carcinoma." (PMID 33025742, 2020). "Mutant EGFR showed the ability to induce HSPs such as HSP60 in lung carcinoma cells suggesting a bidirectional positive feedback loop between HSP60 and EGFR." (PMID 32466334, 2020). "In the present work we evaluated the impact of collagen aging on lung carcinoma cells response to erlotinib-induced cytotoxicity and apoptosis, and on Epidermal Growth Factor Receptor (EGFR) expression and phosphorylation." (PMID 33014812, 2020). "More recently, we and others have provided evidence that ADCs targeting HER‐3 possess potent and specific activity in metastatic melanoma as well as EGFR inhibitor‐resistant lung carcinoma, pancreatic, and colorectal carcinoma." (PMID 32329582, 2020). "In particular, EGFR and KRAS mutations have been rarely found in the same tumours in early studies of genetic alterations in lung cancer and KRAS mutations are regarded as a biomarker of resistance to EGFR TKIs." (PMID 30857358, 2019). "Osimertinib initially gained FDA approval for patients with metastatic EGFR T790M-mutant NSCLC that had progressed on first- or second-generation EGFR TKIs and has subsequently gained approval as a first-line treatment of EGFR-mutant lung cancer." (PMID 31871778, 2019). "NF1 encodes for a negative regulator of KRAS and inactivation leads to EGFR inhibitor resistance in lung cancer." (PMID 31287991, 2019). "Targeting molecular mechanisms of lung cancer is currently the main therapeutic approaches, especially for targeting aberrant epidermal growth factor receptor (EGFR) activity." (PMID 31579447, 2019). "In lung cancer, several generations of small-molecular inhibitors have been developed to target the EGFR tyrosine kinases, such as inhibitors gefitinib, erlotinib, osimertinib, and necitumumab." (PMID 31058077, 2019). "Taken together, the molecular testing of EGFR and KRAS mutations for lung cancer patients has offering advantages for guiding personalized therapy, providing a better patient selection and stratification for clinical management." (PMID 30824880, 2019). "It was reported that KDM5A is required to develop a metastable chromatin state that enables drug resistance in breast cancer and lung cancer treated with EGFR-TKI." (PMID 31448219, 2019). "The prevalence of EGFR mutation in Taiwan was much higher (40.8% to 62.1%) than that in Western countries, indicating that more than half of all lung cancers in Taiwan should be effectively treated with EGFR-TKI." (PMID 31336878, 2019). "Studies in EGFR+ non‐small cell lung cancer (NSCLC) patients with leptomeningeal metastasis (LM) comparing survival rates and gene mutation detection with matched cerebrospinal fluid (CSF) and plasma are relatively scarce." (PMID 31368671, 2019). "The presence of an EGFR-T790M mutation in lung cancer can also lead to the development of EGFR inhibitor resistance but afatinib, targeting ERBB family receptors, can overcome this specific EGFR inhibitor resistance." (PMID 31506424, 2019). "For example, miRNA-143 expression is strongly down-regulated in lung cancer cells, causing elevated c-MYC, NUDT1, OCT4 and EGFR expression, increased tumor cell growth, metastasis and migration." (PMID 31759360, 2019). "In advanced-stage lung cancer patients, the overall sensitivity of NGS in detecting EGFR mutations from plasma ctDNA has been reported to be between 60.9% and 82.1%." (PMID 31185703, 2019).
lung cancer (continued). "Down-regulation of EGFR by miRNA-125a-5p triggered significant apoptosis and enhanced sensitivity of the lung cancer cells to erlotinib in a synergistic way." (PMID 31759360, 2019). "In concordance with recent literature, PI3K–AKT signalling drives acquired drug resistance to EGFR inhibitors in lung cancer." (PMID 31602313, 2019). "Multiple evidence suggests that aberrant EGFR expression and signaling contribute to tumorigenesis as well as progression of various cancer types including lung cancer." (PMID 31817718, 2019). "Consistent with previous reports, treatment by Nutlin-3a led to the upregulation of EGFR in A549 lung cancer cells and MCF-7 breast cancer cells." (PMID 30910997, 2019). "Lung cancer patients on EGFR-TKI treatment had a worse survival outcome if patients had pre-existing COPD." (PMID 31336878, 2019). "The choice of this approach is partially based on the documented synergy of c-Met and EGFR in driving oncogenesis in both EGFR wild type (WT) and mutant lung cancer models, in the setting of acquired resistance to EGFR-TKIs." (PMID 31817278, 2019). "In this study, we determined the EGFR mutation status of LUAD patients using lung cancer tissues and compared the efficiency of the ARMS and SABER/MassARRAY methods in detecting EGFR mutations in ctDNA isolated from the plasma of these patients." (PMID 31185703, 2019). "This provided an explanation, at least to some extent, for the poor unresponsiveness of KRAS-mutant lung cancer patients to the first-generation TKIs targeting EGFR alone." (PMID 31612108, 2019). "Approximately 80% of lung cancers are NSCLC9, and Ras signaling pathway is activated in nearly half of NSCLC patients due either to amplification of EGFR or to activating mutations in EGFR or KRAS3." (PMID 30679620, 2019). "We prospectively assessed the safety and clinical activity of dasatinib and afatinib in combination for patients with resistant EGFR-mutant lung cancer." (PMID 30880334, 2019). "A replicated SNP (rs2293347) in EGFR has also previously corresponded to a protective effect on survival of lung cancer patients." (PMID 31681611, 2019). "EGFR mutation and EML4-ALK fusion gene for lung cancer were common variants described in three systems with the same evidence levels (level I)." (PMID 31383922, 2019). "One target for lung cancer therapy is members of the Epidermal Growth Factor Receptor (EGFR) family." (PMID 31248101, 2019). "Pneumatosis intestinalis occurring during treatment for lung cancer has been reported previously, especially in patients receiving epidermal growth factor receptor (EGFR) tyrosine kinase inhibitors (TKIs), such as gefitinib and erlotinib." (PMID 30819142, 2019). "In vivo generated afatinib-resistant clones of H1975 lung cancer cells showed decreased expression of EGFR, HER2, HER3 and HER4 and increased expression of MET, c-KIT and PDGFRβ." (PMID 31557260, 2019). "In this large scale, nationwide, population-based cohort study, we demonstrated that COPD is a crucial prognostic factor for lung cancer patients treated with EGFR-TKI." (PMID 31336878, 2019). "Third-generation epidermal growth factor receptor (EGFR) tyrosine kinase inhibitors (TKIs) are effective in acquired resistance (AR) to early-generation EGFR TKIs in EGFR-mutant lung cancer." (PMID 32914023, 2019). "In this study, we aimed to investigate targeting epidermal growth factor receptor (EGFR) as a therapeutic approach in KRAS-driven lung cancer cells." (PMID 30935067, 2019). "In this study, we showed that miRNA-125a-5p can inhibit the proliferation of the lung cancer cells and enhance the apoptotic effect of erlotinib by targeting EGFR." (PMID 31759360, 2019). "Recent study showed that pyroptosis was also involved in the response of target therapy in KRAS-, epidermal growth factor receptor (EGFR)—or anaplastic lymphoma kinase (ALK)-driven lung cancer." (PMID 31616642, 2019).
lung cancer (continued). "This ITH assessing genomic engineering method has already been used to study mechanisms of lung cancer cell resistance to EGFR inhibitors and to investigate on combined drug therapies." (PMID 31653140, 2019). "Previous studies indicate that the SLIT/ROBO pathway acts as master regulator for multiple oncogenic signalling pathways including the CD20, mTOR, VEGF and EGFR pathways in several cancer types including lung cancer, colon cancer and lymphoma." (PMID 30857150, 2019). "Resistance can also be acquired to small molecule inhibitors such as the inhibitor of the epidermal growth factor receptor (EGFR) in malignant gliomas and lung cancer or androgen receptor inhibitors in prostate cancer." (PMID 31533363, 2019). "This prompted the launch of another large, randomized, phase 3 clinical trial to compare osimertinib with first-generation EGFR-TKIs as first-line treatment for EGFR mutant lung cancer (FLAURA trial)." (PMID 30625213, 2019). "Mechanistic characterization revealed that this drug combination abrogated expression and activation of membrane receptors and downstream signaling proteins crucial in lung cancer: EGFR, MET, PAK1, PKCι, ERK1/2, AKT, YAP1 and mTOR." (PMID 31660987, 2019). "Because HER3 facilitates EGFR-TKI resistance, our results indicate that the STAT3 blockade is a promising strategy that can be employed to eradicate EGFR-TKI-resistant lung cancers, including KRAS-mutant A549 and T790 M-mutant H1975 cells." (PMID 31619200, 2019). "A total of four EGFR TKIs (gefitinib, erlotinib, lapatinib, and afatinib) are currently in clinical use, with gefitinib, erlotinib, and afatinib being employed to treat lung cancer, while lapatinib (which inhibits both EGFR and Her2) is used for breast cancer." (PMID 31340525, 2019). "Overexpression of EGFR is attributed to the invasion, angiogenesis, proliferation, metastasis, and apoptosis resistance of many tumor cells including lung cancer." (PMID 31759360, 2019). "In lung cancer cells, gefitinib at 5 μM was shown to completely suppress activation of EGFR, Akt and ERK1/2." (PMID 31532771, 2019). "In a mouse model of lung cancer driven by EGFR T790M/L858R mutant, treatment with an antibody MM-121, which blocks ligand-induced activation of ErbB3 and cetuximab, induced durable tumour regression." (PMID 31739412, 2019). "Initial disease progression to crizotinib predominantly occurred in originally-existing lesions, which is consistent with previous studies done in unselected lung cancer populations and in EGFR-mutant patients." (PMID 30866974, 2019). "And 80% of the exosomes purified from lung cancer patients contain EGFR, but the percentage is only about 2% for patients with chronic lung inflammation." (PMID 31608233, 2019). "In the era of targeting therapy for lung cancer, EGFR-TKI have been proven as the pivotal therapeutic role for NSCLC harboring an active EGFR mutation in terms of response rate, PFS and OS." (PMID 31336878, 2019). "Our findings provide evidence for the clinical consideration of using WA in combination with conventional chemotherapy drugs to treat patients with EGFR wild-type lung cancer." (PMID 31319622, 2019). "Using the databases of two lung cancer networks and two lung cancer centers, we molecularly characterized 124 patients with EGFR p.T790M-positive AR to early-generation EGFR TKIs." (PMID 32914023, 2019). "EGFR mutation, KRAS mutation, and EML4-ALK in lung cancer case were commonly annotated resistance information by OKR and QCII." (PMID 31383922, 2019). "Other studies showed that miRNA-145 expression reduced in lung cancer cells, causing elevated c-MYC, NUDT1, OCT4 and EGFR expression, increased tumor cell proliferation, metastasis and migration." (PMID 31554377, 2019). "For instance propranolol, an antagonist of the GNAS coupled β2 andrenergic receptor (ADRAB2), improves prognosis in thick skin melanoma and abrogates EGFR inhibitor resistance acquisition in lung cancer." (PMID 31337866, 2019).
lung cancer (continued). "Taken together, our findings reveal a direct role of miR‐206 in regulating IL‐6/STAT3 pathway and contrarily activated IL‐6/STAT3 signalling mediates the miR‐206 maturation process in gefitinib‐resistant EGFR‐mutant lung cancer cells." (PMID 31507089, 2019). "Gefitinib was developed as an EGFR-TK inhibitor and remarkably reduces tumour growth in many lung cancer patients; however, a drug-resistant cancer cell population emerges after treatment, resulting in recurrence of the disease." (PMID 31289306, 2019). "The most frequent level 1 variants detected were identified in KRAS (colorectal cancer), EGFR (lung cancer), and BRAF (melanoma)." (PMID 30658646, 2019). "We transfected TTF-1 into another EGFR mutant lung cancer cell line (HCC827, EGFR exon 19 deletion) which is intrinsically more resistant to cisplatin than H1975 cells." (PMID 31142791, 2019). "Its clinical utility has been well demonstrated for EGFR T790M testing in lung cancer patients suffering progress after tyrosine kinase inhibitor treatment." (PMID 31620244, 2019). "TFP showed synergism with EGFR inhibitor and chemotherapy drug to overcome drug resistance in lung cancer by inhibiting cancer initiating cells." (PMID 31572198, 2019). "In lung cancer samples, deletions in the EGFR coding regions were more often detected only by tissue, whereas for substitution in EGFR we observed a more prevalent fraction detected only by plasma." (PMID 31296838, 2019). "The emergence and development of epidermal growth factor receptor (EGFR)-targeted tyrosine kinase inhibitors (TKI) led to a new chapter of targeted therapies for lung cancer based on different molecular pathology classifications." (PMID 31696059, 2019). "To detect the expression of IL-22 in lung cancer tissues, we used qRT-PCR to analyze IL-22 mRNA in 20 EGFR-mutant NSCLC patients." (PMID 31750252, 2019). "Erlotinib-resistant lung cancer cells show enhanced sensitivity to navitoclax when combined with an EGFR inhibitor." (PMID 31150457, 2019). "Despite initial dramatic efficacy of epidermal growth factor receptor (EGFR) tyrosine kinase inhibitors (EGFR‐TKIs) in EGFR‐mutant lung cancer patients, subsequent emergence of acquired resistance is almost inevitable." (PMID 30701693, 2019). "Our findings suggest that co-targeting of EGFR and IGFBP7 is an effective strategy for treating EGFR-mutant lung cancer." (PMID 30609749, 2019). "We and others have shown that genomic disruption of the MIG6 gene orchestrates constitutive EGFR signaling resulting in degenerative joint diseases, skin hyperplasia, melanomas, and lung cancer in mice." (PMID 31069016, 2019). "Overexpression of G9a led to increase of HER3 in A549 cells, suggesting that G9a contributed to the overexpression of HER3 in EGFR-positive lung cancers." (PMID 31619200, 2019). "In this study, a cancer spheroid array was made from a p-EGFR-overexpressing cell line (A549 lung cancer cell line)." (PMID 31614722, 2019). "Our findings lay the foundation for understanding the effects of TKIs on the tumor microenvironment and highlight the importance of investigating targeted and immuno-therapy combination strategies to treat EGFR mutant lung cancer." (PMID 31291990, 2019). "In summary, our study first shows that molecular heterogeneity of p.T790M-mutant lung cancer with AR to early-generation EGFR TKIs influences efficacy of third-generation inhibitors." (PMID 32914023, 2019). "In EGFR mutant lung cancer cells resistant to TKIs, CX-4945 was reported to sensitize cells and induce autophagy; however, cell recovery was observed upon CX-4945 withdrawal." (PMID 31277672, 2019). "Non-small cell lung cancer (NSCLC) represents over 85% of all lung cancers, and up to 50% of Asian NSCLC patients harboring epidermal growth factor receptor (EGFR) gene mutations." (PMID 31526464, 2019). "BDNF-mediated activation of EGFR has been observed in lung cancer and suggests BDNF/TrkB/EGFR cross-talk is a more general mechanism promoting BM." (PMID 30796353, 2019).